RTEL1-TNFRSF6B (RTEL1-TNFRSF6B readthrough (NMD candidate))
Gene: Protein-coding gene on chromosome 20 (63,659,300 to 63,698,684, forward strand). Ensembl gene ENSG00000026036.
Genetic constraint (gnomAD): Missense variants: 935 observed, 1,060.1 expected, observed/expected ratio (o/e) 0.88, 90% interval 0.83 to 0.93. Synonymous variants: 496 observed, 431.94 expected, observed/expected ratio (o/e) 1.15, 90% interval 1.07 to 1.24.